ENPP1 (ectonucleotide pyrophosphatase/phosphodiesterase 1)
Diseases named in the same sentence as ENPP1 in open-access papers (continued):
Sharing a sentence is not in itself a finding about the gene and the disease.
breast carcinoma (continued). "Conversely, we predict that ENPP1-high breast cancer patients will greatly benefit from a combination of ENPP1 inhibition with anti-PD-1/anti-PD-L1 or PARPi treatments." (PMID 38117852, 2023). "Our previous work showed that ENPP1 inhibitors have efficacy in murine models of primary breast cancers with limited effect size." (PMID 38117852, 2023). "Together, we conclude that ENPP1’s catalytic activity restricts adaptive immune cell infiltration, contributing to its role in promoting breast cancer growth and metastasis." (PMID 38117852, 2023). "ENPP1 expression was found to be significantly high in several cancer patients (TCGA dataset), including in breast cancer primary tissues, which showed the highest ENPP1 expression." (PMID 36235254, 2022). "Cumulatively, these data suggest that ENPP1 has high gene and protein expression levels across cancer types, especially in breast cancer." (PMID 36235254, 2022). "ENPP1 expression was considerably high in breast cancer samples (median value: 4.27 log2(TPM+1)) and significantly low in lung cancer patients (median value: 0.8 and 0.5 log2(TPM+1) in lung adenocarcinoma and lung squamous cell carcinoma, respectively)." (PMID 36235254, 2022). "The expression of ENPP1 in endometriosis, lung cancer cells, breast cancer cells and glioblastoma was significantly increased." (PMID 33635867, 2021). "Consistent with previous studies in lung cancer and breast cancer, our present study found that ENPP1 protein expression was significantly higher in HGSOC than in ovarian serous cystadenoma, but almost no expression was found in normal ovarian epithelium." (PMID 33635867, 2021). "Recently, a report has identified that miR-27b-3p serve as a cancer suppressor in breast carcinoma stem cell generation through inactivating Ectonucleotide Pyrophosphatase/Phosphodiesterase 1 (ENPP1), to attenuate chemoresistance ability." (PMID 32782028, 2020). "Metformin modulates the following axes: miR-miR-708/CD47 in breast cancer, miR-27b/ENPP1 in breast cancer, 26a/EZH2 in pancreatic cancer, and blocks TGFβ1-induced upregulation of miR-181a and downregulation of miR-96 in breast cancer." (PMID 32512882, 2020). "The role of ENPP1 in cancer is exemplified by the observations of enhanced tumor metastasis to the bone from breast cancer, for example, by over-expression of ENPP1." (PMID 31752288, 2019). "A qRT–PCR analysis revealed elevated ENPP1 expression in breast cancer tissues that had lower miR-27b expression than normal tissues." (PMID 26065921, 2015). "The results presented here demonstrate that ENPP1 also regulates the drug resistance of the SP fraction in breast cancer." (PMID 26065921, 2015). "By qRT-PCR and Western analysis we found that expression of Enpp1 was elevated in human breast cancer cell lines known to produce bone metastasis in animal models compared to non-metastatic and normal mammary epithelial cell lines." (PMID 23861746, 2013). "Taken together, these data suggest a potential role for Enpp1 in the development of breast cancer bone metastasis." (PMID 23861746, 2013). "Indeed, we observed that tumor exosomes exhibit high ENPP1 expression in tissue samples from lung cancer and breast cancer patients." (PMID 38498770, 2024). "Notably, breast cancer patients exhibiting reduced ENPP1 expression demonstrate elevated levels of immune infiltration." (PMID 39318624, 2024). "We next correlated tumor exosomal ENPP1 levels with CD8+ T cells and CD4+ T cells density across breast cancers and lung cancers, and found that total ENPP1 of breast cancers or lung cancers tissue inhibited the immune infiltration of CD8+ T cells and CD4+ T cells." (PMID 38498770, 2024). "We determined that ENPP1 expression is an on/off switch that controls whether breast cancer will metastasize in a STING-dependent manner in mouse models." (PMID 38117852, 2023). "There is mounting evidence that ENPP1 promotes breast cancer in humans." (PMID 38117852, 2023).
breast carcinoma (continued). "Breast cancer patients with low ENPP1 expression have hot tumors and responded completely to pembrolizumab with 7-y metastasis-free survival, demonstrating ENPP1 levels can be used as a biomarker for patient stratification and should also be targeted for immunotherapy." (PMID 38117852, 2023). "After delineating the molecular and cellular mechanisms governing the deterministic role of ENPP1 in metastasis of murine breast cancers, we asked whether these mechanistic insights and disease outcomes are conserved in humans." (PMID 38117852, 2023). "Additionally, many studies indicate that ENPP1 is highly expressed in many cancers, including lung cancer, ovarian cancer and breast cancer, and that this overexpression is a strong indicator of poor prognosis in different cancers." (PMID 36761762, 2023). "While this study focused on the roles of ENPP1 in the context of breast cancers, our findings could potentially be generalized to other types of immunologically cold tumors." (PMID 38117852, 2023). "Therefore, we postulate that deactivating ENPP1’s cGAMP hydrolysis activity to enhance paracrine STING signaling will be a promising therapeutic approach to impede breast cancer metastasis." (PMID 38117852, 2023). "In addition, low ENPP1 expression in pre-treatment biopsy samples obtained from breast cancer patients predicted their response to pembrolizumab (anti-PD-1) as a neoadjuvant therapy and distant-metastasis free survival (DMFS) up to 7 y." (PMID 38117852, 2023). "In human breast cancer cell lines and murine breast cancer models, inhibition of ectonucleotide pyrophosphatase phosphodiesterase 1 (ENPP1), a hydrolase of cGAMP, was recently found to increase extracellular cGAMP levels and synergize with radiotherapy to prevent tumor growth." (PMID 36387071, 2022). "Enpp1 encodes an ecto-nucleotide pyrophosphatase/phosphodiesterase (ENPP), which is expressed in osteoclasts, and which promotes calcification of bone, and facilitates breast cancer metastasis to the bone." (PMID 25674539, 2015). "Furthermore, miR-27 targets ectonucleotide pyrophosphatase/phosphodiesterase family member 1 (ENPP1) and regulates the tumorigenicity and drug resistance of breast cancer cells." (PMID 26712794, 2015). "Growth of breast cancer cells under mammosphere culture conditions, which are used widely for the enrichment of breast CSCs32, induced downregulation of miR-27b and suppression of proteasome activity, leading to an accumulation of ENPP1." (PMID 26065921, 2015). "To determine the molecular mechanism by which ENPP1 induces drug resistance in only a small population of breast cancer cells, we investigated the fate of this protein in MCF7-luc cells stably expressing ENPP1-MF (MCF7-luc ENPP-MF), which was generated using a lentivirus vector." (PMID 26065921, 2015). "In this study, we identified the ectoenzyme ectonucleotide pyrophosphatase/phosphodiesterase I (Enpp1) as being overexpressed in human primary breast cancer relative to normal mammary epithelium and provide the first evidence of its potential to foster the development of bone metastasis." (PMID 23861746, 2013). "Importantly, our work provides evidence that ENPP1 promotes breast cancer initiation." (PMID 38117852, 2023). "In addition, since elevated expression of ENPP1 was observed in breast cancer patients, evaluation of ENPP1 expression in primary breast cancer tissues may be useful for predicting malignant potential and response to chemotherapy." (PMID 26065921, 2015). "Ectonucleotide pyrophosphatase/phosphodiesterase 1 (ENPP1), 1st identified in breast cancer and subsequently in multiple other cancer types, is an innate immune checkpoint regulator that recently emerged as a promising biomarker and therapeutic target." (PMID 41496120, 2026).
breast carcinoma (continued). "By upregulating the expression of ectonucleotide pyrophosphatase/phosphodiesterase 1 (ENPP1), HER2Δ6 in breast cancer cells can lower IFN expression, produce adenosine with immunosuppressive effects, and inhibit T cell and macrophage infiltration in tumors." (PMID 40032844, 2025). "Ectonucleotide pyrophosphatase/phosphodiesterase family member 1 (ENPP1), that is negatively modulated by metformin, is up-regulated in this type of breast cancer." (PMID 33849540, 2021). "Recent study shows that, ENPP1 upregulates ABCG2 transporter, increase tumor seeding ability and resistant to conventional chemotherapy in breast cancer." (PMID 33635867, 2021). "ENPP1 promotes the expression and cell surface localization of ABCG2 which is involved in the development of multidrug resistance, for example, in breast cancer, esophageal cancer, lung cancer." (PMID 32512882, 2020). "Therefore, we hypothesized that ENPP1 is degraded by the 26S proteasome in breast cancer cells." (PMID 26065921, 2015). "To confirm the prognostic values of ENPP1 and ABCG2 expression in other types of cancer, we examined the expression levels of these mRNAs in luminal B and basal-type breast cancer samples." (PMID 26065921, 2015). "Altogether, ENPP1 blockade represents a strategy to exploit cancer-produced extracellular cGAMP for controlled local activation of STING and is therefore a promising therapeutic approach against breast cancer." (PMID 38117852, 2023). "Furthermore, MTX promoted STING pathway activation by inhibiting ENPP1 and provided clinical potential for combining MTX with radiation therapy for the treatment of breast cancer in which ENPP1 shows hyper-expression." (PMID 34677780, 2022). "Although elevated expression of ABCG2 or ENPP1 was not correlated with recurrence of breast cancer, co-expression of ABCG2 and ENPP1 was moderately associated with poor prognosis (HR=1.84; P=0.062)." (PMID 26065921, 2015). "Western blot analysis revealed the presence of ENPP1 in exosomes derived from various human tumor cells lines, which included lung cancer A549, melanoma A375, oral cancer CAL27, colorectal cancer SW480, cervical cancer HeLa, breast cancer MDA‐MB‐231, and glioma U251." (PMID 38498770, 2024). "In addition, in the triple negative (basal-type) breast cancer cell line MDA-MB-231, which shows low expression of endogenous ABCG2, an inverse correlation between ENPP1 and miR-27b expression was observed, although the cell surface localization of ABCG2 was not induced by knockdown of miR-27b." (PMID 26065921, 2015). "The two breast cancer cell lines we had previously identified 4T1 and EMT6 expressed Enpp1, but a third E0771 did not." (PMID 39622844, 2024). "To exclude the possibility that ARMCX1, ENPP1 and MCT2 are essential for breast cancer growth regardless of the MGDAs, we tested whether colony formation was enhanced by MGDAs in MDA-MB-468 and SK-BR3 cells ectopically expressing these genes." (PMID 28281525, 2017).
Obesity (29 papers, 2007 to 2025). Accumulation of substantial excess body fat. "The underlying regulatory mechanism of Enpp1 expression in hepatocytes deserves further investigation, especially in the context of metabolic diseases such as obesity and diabetes." (PMID 29513794, 2018). "Specifically, both ESP and ENPP1 mutations and over expression are associated with abnormalities in glucose metabolism, insulin sensitivity, obesity and diabetes." (PMID 24839967, 2014). "Although the association between both MC4R and NEGR1 and risk of obesity has been confirmed in a plethora of studies and populations, the ENPP1 association signal with obesity is more controversial." (PMID 23375129, 2013). "Of note, the risk alleles for obesity or increased BMI were the same between Europeans and Mexicans, except for the risk allele of ENPP1 rs7754561 (in Europeans) that showed a protective effect in Mexicans." (PMID 23375129, 2013). "The region also contains several genes associted with obesity or metabolic syndrome such as ENPP1 with obesity and risk of glucose intolerance and type 2 diabetes, SGK1 with insulin secretion in type 2 diabeties." (PMID 23977060, 2013). "In a large study, a three-polymorphism “risk haplotype” of the ENPP1 gene has been described to be associated with obesity and T2D in both children and adults." (PMID 23762820, 2013). "Elucidation of the interplay of ENPP1 in increased susceptibility to 2DM, obesity and CAD will provide recommendations for the underlying shared mechanisms of these complex common diseases." (PMID 22697793, 2012). "The liver proteins INSR, PTPN1, and ENPP1 are associated with diabetes mellitus type 2 and obesity." (PMID 35259090, 2022). "Our study pointed out the role of MC4R rs17782313 and ENPP1 rs1044498 in maternal and neonatal obesity risk in correlation with BMI, MUAC and TST and BIA, which could be useful for diagnosing obesity in mother-newborn couples." (PMID 31350533, 2019). "Similarly, a study performed on children with obesity underlined the potential role of K121Q ENPP1 polymorphism in not only early perturbations of glucose and insulin metabolism but also subsequent obesity development." (PMID 30338250, 2018). "Furthermore, we found nominal associations between risk of obesity or BMI and the following SNPs: ENPP1 rs7754561, MC4R rs17782313 and NEGR1 rs2815752." (PMID 23375129, 2013). "Furthermore, we found nominal associations between obesity risk or BMI variation and the following SNPs: ENPP1 rs7754561, MC4R rs17782313 and NEGR1 rs2815752." (PMID 23375129, 2013). "Interestingly, ENPP1 gene variation was found to be independently associated with obesity-related traits in Mexican American pedigrees by a positional candidate gene approach." (PMID 22043164, 2011). "ENPP1 K121Q has been previously associated with human obesity." (PMID 17849011, 2007). "Findings from another investigation showed that overexpression of Enpp1 in subcutaneous adipose tissue contributed to the development of obesity." (PMID 39972484, 2025). "The population of Indonesia has a high genetic diversity; thus, investigation of the association of SNPs in ENPP1 and ADIPOQ genes with obesity, and its related traits, is of potential interest." (PMID 34208364, 2021). "Our study did not significantly implicate a positive correlation between the K121Q SNP of the ENPP1 gene and obesity." (PMID 34208364, 2021). "Our study pointed out the role of MC4R rs17782313 and ENPP1 rs1044498 genotypes in obesity determinisms in mothers and their newborns in correlation with BMI, MUAC, TST and bioimpedance parameters." (PMID 31350533, 2019). "Interestingly, the same authors identified a different pattern for the risk allele of ENPP1 rs7754561 in Mexican individuals showing a protective role in obesity development compared with that in European individuals where the same gene presented positive associations with obesity risk." (PMID 30338250, 2018).
Obesity (continued). "A large study performed on 1,685 obese and normal-weight Mexican children found nominal associations between different gene polymorphisms, like those in ENPP1 rs7754561 and MC4R rs17782313, and obesity risk or BMI." (PMID 30338250, 2018). "A positional cloning experiment led to identification of ectonucleotide pyrophosphatase/phosphodiesterase 1 (ENPP1) as a possible contributor to obesity and type 2 diabetes in humans." (PMID 25825681, 2015). "Given the detrimental effects of obesity on bone, we next considered the effects of chronic high-fat challenge on the bone physiology of Enpp1−/− mice." (PMID 25368121, 2014). "The association of six European obesity-related SNPs in or near FTO, NPC1, ENPP1, NEGR1, GNPDA2 and MC4R genes with risk of obesity was tested in 1,463 school-aged Mexican children (Ncases = 514; Ncontrols = 949)." (PMID 23375129, 2013). "The function of the gene can be directly related to obesity and type 2 diabetes as ENPP1 inhibits insulin receptor signaling." (PMID 22043164, 2011). "Clearly, mechanisms for adipogenesis and onset of obesity are complex, and alternative pathways can compensate for the inhibitory effects of ENPP1 on adipogenesis." (PMID 17849011, 2007). "In both studies, we genotyped six SNPs that are known to be associated with risk of obesity in European populations: rs17782313 near MC4R; rs2815752 near NEGR1; rs7754561 near ENPP1; rs1805081 in exon 6 of NPC1; rs10938397 near GNPDA2 and rs1421085 in intron 1 of FTO." (PMID 23375129, 2013). "This large case-control study further supports the hypothesis that the T2D risk contribution of ENPP1, ADIPOQ, PPARG and TCF7L2 SNPs may be modulated by obesity status." (PMID 18498634, 2008). "ENPP1, ADIPOQ, PPARG and TCF7L2 single nucleotide polymorphisms (SNPs) have previously been associated with T2D and have shown variable significance amongst different classes of obesity." (PMID 18498634, 2008). "Therefore, it seems necessary to compare the results obtained with other potential indicators in the future, like molecular indicators including variants of different risk alleles to determine polygenic or common obesity, including FTO, TNF-α, MC4R, ENPP1 genes, etc.." (PMID 37761477, 2023). "Similarly, recent studies proved that the variant allele of ENPP1 rs104449 increases the risk for obesity and type 2 diabetes mellitus, but no study established the role of this SNP in the newborn’s BW and pregnant woman’s nutritional status." (PMID 31350533, 2019). "Furthermore, we detected several obesity candidate genes, for example, ENPP1, CTSL, and ABHD12B." (PMID 26482556, 2015). "It was found that the expressions of ENPP1, MC3R, and SIM1 were significantly different between controls and obesity." (PMID 39351493, 2024). "Recently, other genes that are thought to have an impact in the development of obesity were discovered, such as: melanocortin receptor (MCR) MC4R, MC3R, MC2R, and also nucleotide pyrophosphatase/phosphodiesterase (ENPP1)." (PMID 31350533, 2019). "In this study, we identified, for example, the genes ENPP1, CTSL, CIDE-C, and ABHD12B as potential causal genes for obesity, and further validation (e.g., by qPCR in a large human population) and investigation of these genes might lead to biomarkers for obesity." (PMID 26482556, 2015). "Despite the recognized importance of ectonucleotide pyrophosphatase/phosphodiesterase-1 (NPP1) in the regulation of bone mineralization, its contribution to obesity and type 2 diabetes remains less clear." (PMID 25368121, 2014). "It was previously demonstrated that the genetic effects of variants associated with either insulin secretion (like for GCK, KCNJ11 or TCF7L2) or insulin action (for ENPP1, ADIPOQ or PPARG) may be modulated by the obesity status or adiposity." (PMID 19368707, 2009). "Defective adipocyte maturation related to increased ENPP1 function does not exclude the possibility of obesity." (PMID 17849011, 2007).